MB (myoglobin)
Diseases named in the same sentence as MB in open-access papers (continued):
Sharing a sentence is not in itself a finding about the gene and the disease.
myocardial infarction (continued). "Similarly, the nitrite reductase activity of myoglobin reduces myocardial infarction in mice via NO upon nitrite treatment; this response is lacking in myoglobin−/− mutants." (PMID 41480195, 2025). "Therefore, confirming death due to acute myocardial infarction relies on several biochemical indicators of myocardial damage in the clinical practice, including troponin, myoglobin, and creatine kinase isoenzymes." (PMID 38338938, 2024). "Myoglobin is released into the blood stream within the first few hours when the heart or skeletal muscles are injured; therefore, it is a potential biomarker for detecting acute myocardial infarction." (PMID 37420790, 2023). "Myoglobin and CK-MB are also sensitive markers of acute myocardial infarction (AMI)." (PMID 37178386, 2023). "Myoglobin is released into the circulation as a result of skeletal muscle damage or a heart attack, may be present in urine in high concentrations, and is highly nephrotoxic." (PMID 37174905, 2023). "However, myoglobin has a very short half-time in serum of only a couple of minutes and is therefore seldom measured in suspected RM or myocardial infarction." (PMID 35207410, 2022). "Myoglobin: an early biochemical marker for the diagnosis of acute myocardial infarction." (PMID 34008817, 2021). "The combination of SPR sensor with advantages of molecular imprinting-based synthetic receptors was reported in the detection of cardiac biomarkers used to diagnose acute myocardial infarction such as myoglobin, creatine kinase-myocardial band, and cardiac troponins." (PMID 32549390, 2020). "Examples of diseases that can reliably be diagnosed through salivary analysis are pancreatic (miR-3679-5p and miR-940), lung (cytokines IL1RN, IL1B, CXCL10), and breast cancers (phenylalanine, tryptophan), as well as myocardial infarction (C-reactive protein, myoglobin, and myeloperoxidase)." (PMID 32019170, 2020). "Free radical cardiac myoglobin and other sources play an important role in myocardial infarction." (PMID 31367480, 2019). "Serum myoglobin is one of the earliest markers for the diagnosis of acute myocardial infarction." (PMID 30519882, 2018). "It is worth mentioning that myoglobin is the main marker of early acute myocardial infarction as the concentration of myoglobin could indicate myocardial damage." (PMID 27801833, 2016). "Myoglobin is one of the early biomarkers for acute myocardial infarction." (PMID 25530617, 2014). "Cardiac Tn measured by automated standard assays is superior to all other available biomarkers in clinical practice, including myoglobin, the MB fraction of creatine kinase, myeloperoxidase, and heart fatty acid-binding protein, for the diagnosis of acute myocardial infarction." (PMID 22262955, 2012). "Also found are fatty acid binding protein and myoglobin which are markers of acute myocardial infarction." (PMID 20808962, 2010). "Previously, before the introduction and clinical adoption of high-sensitivity cardiac troponin (hs-cTn) assays, creatine kinase-MB (CK-MB) and myoglobin were the main tools for diagnosing myocardial infarction (MI) in adults." (PMID 39857049, 2025). "On the basis of the markers of myocardial necrosis in serum samples (TnI, CK, CK-MB, and myoglobin) and electrocardiography, according to the accepted standards, non-ST-elevation myocardial infarction was recognized in 30% of the patients, while ST elevation myocardial infarction in 70%." (PMID 33407375, 2021). "Meanwhile, some researches had found that the level of CAIII protein was almost unchanged after myocardial infarction thrombolysis, while myoglobin concentration increased significantly, so CAIII protein could be used in the differential diagnosis of acute myocardial infarction." (PMID 34665375, 2021). "Hence, monitoring the myoglobin level could facilitate the early detection and appropriate therapeutic measures for myocardial infarction." (PMID 33799932, 2021).
myocardial infarction (continued). "Myoglobin is a potential indicator of heart attacks in human, and its detection in human blood above a certain threshold could result in the early detection of heart attack and its prevention." (PMID 30393684, 2018). "Additionally, we identified differentially expressed cardiac biomarker proteins specific to each time point, such as cardiac troponin T (cTnT) (Log2 Fold = 2.212, 48 h) positively associated with myocardial infarction and myoglobin (MB) (Log2 Fold = −2.8113, 24 h) was negatively associated." (PMID 41399465, 2025). "MagMOF has been successfully used to detect acute myocardial infarction (AMI) biomarkers with high sensitivity, including creatine kinase isoenzyme (CK-MB), troponin I (CTn I), and myoglobin (Mb)." (PMID 37202433, 2023). "FGF4+AA-treated BG01 hESC-CMs robustly released acute myocardial infarction (AMI) biomarkers (cTnI, CK-MB, and myoglobin) into culture medium in response to hypoxic injury." (PMID 34685725, 2021). "High concentrations of salivary CRP, myoglobin and MPO, for example appear after myocardial infarction." (PMID 24915044, 2014). "Furthermore, in clinical practices, markers such as cTnI, Myoglobin (MB), and Creatine kinase M (CKM) are quantified in blood to diagnose myocardial infarction resulting from IR injury." (PMID 38693114, 2024). "Myoglobin should not be used alone to confirm a diagnosis of acute myocardial infarction; instead, it should be combined with other heart-specific markers like TNI or TNT to boost diagnostic value." (PMID 36264449, 2022). "Although CK-MB levels increase significantly in 6-8 hours and myoglobin levels increase significantly 3 hours after myocardial infarction, they are not cardiac-specific markers and cannot distinguish myocardial damage from skeletal muscle injury." (PMID 28077344, 2017). "Myoglobin is no longer useful in the routine assessment of patients for possible acute myocardial infarction (AMI)." (PMID 26317036, 2014). "They focused on the detection of cardiac markers of heart attack and acute myocardial infarction (AMI) such as BNP, CK-MB, Myoglobin and Troponin I. The use of impedimetric sensing is advantageous as it is label-free, not requiring the use of any fluorescent reagents." (PMID 22163570, 2010). "Importantly, creatine kinase-MB and myoglobin levels were not increased in patients with a history of myocardial infarction or ischemic cardiac events." (PMID 22300528, 2012). "Additionally, myoglobin is not a reliable parameter for myocardial infarction in general." (PMID 23062276, 2012).
COVID-19 (73 papers, 2020 to 2026). A disease caused by infection with severe acute respiratory syndrome coronavirus 2. "According to current evidence, elevation of cardiac injury biomarkers, such as troponin and hs-TnI, CK-MB, myoglobin and NT-proBNP, is associated with COVID-19 severity and mortality." (PMID 36016322, 2022). "A meta-analysis involving 4189 patients showed that more severe COVID-19 was associated with increased troponin, creatine kinase, myoglobin, and NT-proBNP." (PMID 32805730, 2020). "The risk factors for severe cases of COVID-19 in Guangzhou included older age, Wuhan exposure history greater than 2 weeks, diarrhea, elevated Myoglobin, elevated WBC and CRP, and CKD." (PMID 32805730, 2020). "Several studies have associated elevated levels of myoglobin with COVID-19 severity." (PMID 33727641, 2021). "Taking together, the previous studies support our findings and thus we report that CRP and myoglobin could prove efficient prognostic biomarkers for COVID-19 associated mortality." (PMID 33727641, 2021). "Myoglobin has been identified as a predictor of mortality in both severe and critical forms of COVID-19." (PMID 40149648, 2025). "Our analysis identified that combined CKMB and myoglobin levels were significant predictors of a prolonged hospital stay in COVID-19 patients." (PMID 40149648, 2025). "CKMB and myoglobin specifically show positive relationships with longer hospital stays, indicating their relevance in predicting COVID-19 severity and complications." (PMID 40149648, 2025). "Studies by Parohan, Yaghoubi, and Seraji in turn have clarified the link between elevated cardiac injury markers (LDH, CK-MB, CK, and myoglobin) and increased mortality due to COVID-19." (PMID 40283636, 2025). "AKI occurrence in severe COVID-19 was multifactorial, with elevated myoglobin and prolonged corticosteroid therapy emerging as factors independently associated with AKI, while higher hemoglobin exerted a protective effect." (PMID 41462971, 2025). "From a clinical standpoint, our findings argue for early monitoring of CK, myoglobin, and LDH as part of a renal risk panel in hospitalized COVID-19 patients, especially those with worsening muscular symptoms or unexplained enzyme elevations." (PMID 41462971, 2025). "For COVID-19-related multisystem inflammatory syndrome suspicion, we studied cardiac function and thromboembolic panel with D-dimer, T troponin, myoglobin, and pro-BNP." (PMID 38790534, 2024). "COVID-19 patients with a peak in myoglobin levels at day 2 had more VFDs compared to several clusters with other trajectories of this biomarker." (PMID 37582864, 2023). "Other biomarkers like myoglobin and troponin I have been positively correlated with significantly higher risks of severe disease and mortality among COVID-19 patients." (PMID 37662953, 2023). "This and other studies also provide evidence for the use of cardiac biomarkers, such as troponin I, myoglobin, and CK-MB, in the diagnosis and prognosis of cardiac injury in COVID-19 patients." (PMID 37568870, 2023). "Severe COVID-19 is accompanied by increased MB, CRP, Tbil, Dbil, Neu counts and decreased LYM counts, PLT, and Cr clearance rate." (PMID 37223120, 2023). "In patients with severe forms of COVID-19, the increase in the serum myoglobin has been considered more significantthan elevated TnI, being associated with increased mortality." (PMID 36013560, 2022). "Several studies have also investigated the prognostic value of creatine kinase and myoglobin—often together with hs-cTn—in COVID-19." (PMID 35326373, 2022). "Here, we analyzed the ROC of Interleukin 2 receptor, Interleukin 6, glucose, NT proBNP, and myoglobin for the diagnosis of severe COVID-19 in six age groups." (PMID 36233840, 2022). "The serum myoglobin was an effective predictor of the prognosis in COVID-19 hospitalized patients, the higher serum myoglobin levels were related to poor prognosis of COVID-19 patients." (PMID 36275701, 2022).
COVID-19 (continued). "The prevalence of elevated cardiac troponin I (cTnI) and myoglobin (Mb) in the general population with COVID-19 was 22.9 (19-27%) and 13.5% (10.6-16.4%), respectively." (PMID 34869669, 2021). "A significant number of COVID-19 patients experience rhabdomyolysis due to COVID-19 directly binding the porphyrin substrate of myoglobin, leading to the release of hemoprotein and iron, which induces inflammation and muscle breakdown." (PMID 32708430, 2020). "Amongst them, age, WBC, NEU, GFR, and Myoglobin were selected by multivariate analysis as candidates of scoring system for prediction of disease severity in COVID-19." (PMID 32582575, 2020). "One unexpected finding was that 57 (35.2%) critically ill patients with COVID-19 were with increased levels of myoglobin." (PMID 32410714, 2020). "Our analysis revealed that severe COVID-19 cases have elevated levels of biomarkers of cardiomyocytes injury such as Troponin I, CK-MB, CK and myoglobin." (PMID 32879731, 2020). "In the context of COVID-19, elevated myoglobin could signal more severe cardiovascular or musculoskeletal damage, which would lead to longer hospital stays due to complications, the need for additional care, or prolonged recovery." (PMID 40149648, 2025). "Similarly, findings were reported that the serum level of myoglobin in the dead group was higher than in the survival, and an increase in myoglobin was a valuable predictor of the severity of COVID-19." (PMID 39164612, 2024). "Elevated levels of myoglobin, troponin, creatine kinase-MB, plasma interleukin-6, lactate dehydrogenase (LDH), and N-terminal pro-b-type natriuretic peptide (NT-proBNP) have been found in COVID-19-associated myocardial injuries." (PMID 37009373, 2023). "Further supporting the similarity between bacterial sepsis and COVID-19-induced viral sepsis, we observed an elevation of factors associated with oxidative stress (e.g., MPO) and factors released from damaged (organ) tissue (NGAL, Cystatin C, myoglobin)." (PMID 36851312, 2023). "Our findings are in line with observations of myoglobin as an important COVID-19 biomarker." (PMID 37662953, 2023). "In addition to the triad neutrophilia-lymphopenia-thrombocytopenia and increased concentrations of CRP, D dimer, and procalcitonin, myoglobin was found to be elevated in patients with severe COVID-19, which correlates with a hypoxemic state." (PMID 36016660, 2022). "MB, TLR4 and ALB are involved in coronavirus biology, and are associated with COVID-19 prognosis." (PMID 36275701, 2022). "Additionally, myoglobin was elevated in women included in the severe group (p = 0.030), while cholesterol levels were lower (p < 0.0001) than those with the mild form of COVID-19." (PMID 36016660, 2022). "However, severe COVID-19 patients, especially those who develop rhabdomyolysis, express exponential alterations in CK and myoglobin, which denotes the importance of assessing these parameters in COVID-19 patients who are emaciated or experiencing myalgia." (PMID 34113379, 2021). "To find an alternative disease timer, we compared the testing frequency of routine laboratory parameters such as the acute phase inflammatory marker CRP, the inflammatory cytokine interleukin 6 (IL-6), myoglobin and cardiac troponin that have previously been correlated to COVID-19 severity." (PMID 34307391, 2021). "Of cardiac biomarkers, Myoglobin specifically could efficiently predict COVID-19 severity in its early stages." (PMID 33727641, 2021). "Myoglobin was also included in the COVID-19 severity score table as one of the biomarkers." (PMID 32805730, 2020). "Increased levels of lactate dehydrogenase (LDH), creatine kinase (CK), high-sensitivity cardiac troponin I (hs-cTnI), myoglobin, creatinine, urea, alanine aminotransferase (ALT), aspartate aminotransferase (AST), and total bilirubin were highly associated with severe COVID-19." (PMID 32765952, 2020). "Similar to hemoglobin, myoglobin is also affected by COVID-19." (PMID 32708430, 2020).
COVID-19 (continued). "Elevated levels of LDH and myoglobin were observed in COVID-19 patients." (PMID 32765952, 2020). "However, there was another research found that both gross changes in albumin and myoglobin may early disclose COVID-19 fatal outcomes." (PMID 39164612, 2024). "However, raised myoglobin levels are more specific for cardiac insult in COVID-19 patients." (PMID 37009373, 2023). "Other cardiac and non-cardiac biomarkers are common findings in COVID-19-associated cardiovascular disease, including creatine kinase (CK)-MB, myoglobin, D-dimer, brain natriuretic peptide (BNP) and its N-terminal pro-hormone (NT-proBNP), and neutrophil-to-lymphocyte ratio." (PMID 35572561, 2022). "Our findings suggest that myoglobin may be a reliable marker of illness reflecting general physiological disturbance and help to assess prognosis and treatment response in patients with COVID-19." (PMID 34458331, 2021). "In our study, myoglobin, creatine kinase, BNP, and TNI were increased in severe patients compared to non-severe patients, and myoglobin was a risk factor for severe patients, which indicated that COVID-19 may be related to acute cardiac injury." (PMID 32805730, 2020). "For instance, studies have demonstrated that elevated cardiac biomarkers such as troponin, myoglobin, and CKMB correlate with worse clinical outcomes, including prolonged hospitalizations and higher mortality rates in COVID-19 patients." (PMID 40149648, 2025). "Troponin, myoglobin, and CK-MB levels have been identified as reliable predictors of respiratory complications, such as acute respiratory distress syndrome (ARDS), in COVID-19 patients." (PMID 40149648, 2025). "LDH levels in patients with COVID-19 correlated significantly with CRP (ρ = 0.31, p = 0.024), albumin (ρ = -0.40, p = 0.002), CKMB_M (ρ = 0.31, p = 0.028), and myoglobin (ρ = 0.29, p = 0.036)." (PMID 37965268, 2023). "At baseline, for non-KTRs, differences in several cytokines and vascular mediators were observed when the COVID-19 patients were compared with the HCs, except for ADAMTS-13, myoglobin, IL-9, G-CSF, and TNF-α." (PMID 38005844, 2023). "Our data demonstrated that serum biomarkers HMGB1, myoglobin, FABP3 and troponin I were significantly altered during the initial phase of COVID-19." (PMID 37662953, 2023). "Next, we further analyzed the possible binding of vitamin D with the seven COVID-19/HCC targets (HMOX1, MB, TLR4, ALB, TTR, ACTA1 and RBP4) identified previously and found that vitamin D only binds to MB and RBP4." (PMID 36275701, 2022). "During hospitalization, the mean peak concentration of cTnI, creatine kinase MB (CK-MB), myoglobin (Myo), and B-type natriuretic peptide (BNP) was higher in COVID-19 patients with DM." (PMID 36123740, 2022). "By taking the intersection of COVID-19/HCC genes and vitamin D-associated targets, we obtained seven overlapping genes (HMOX1, MB, TLR4, ALB, TTR, ACTA1 and RBP4) of vitamin D against COVID-19/HCC." (PMID 36275701, 2022). "Consistently, our study also demonstrated that HTN was the most common comorbidity (almost 19.3%) observed in hospitalized COVID-19 patients and also, these patients displayed an increase of cardiac injury markers, such as LDH, CK, and myoglobin." (PMID 34789776, 2021). "An important complication of COVID-19 is acute myocardial injury (AMI), which is reflected specifically by troponin I and creatine kinase-MB." (PMID 33106442, 2020). "COVID-19 patients with DM showed as older ages, higher levels of C-reactive protein (CRP), myoglobin, alanine transaminase (ALT), and aspartate transaminase (AST)." (PMID 33381599, 2020). "The pronounced cytolytic syndrome in the patients who developed AKI (Group A), demonstrated by elevated serum values for myoglobin, LDH, and CK, may represent a mechanistic contributor to AKI in COVID-19, beyond being a marker of disease severity." (PMID 41462971, 2025). "Thus, CKMB, myoglobin, and troponin I have the most significant correlations with LOS in COVID-19 patients." (PMID 40149648, 2025).